RHOB (ras homolog family member B)
Diseases named in the same sentence as RHOB in open-access papers (continued):
Sharing a sentence is not in itself a finding about the gene and the disease.
colitis (5 papers, 2015 to 2025). Inflammation of the colon. "Taken together, these data suggest that the increased abundance of P. denticola and A. rava are associated with decreased colitis in RhoB-deficient mice." (PMID 36114582, 2022). "We examined the role of RhoB in colitis using both heterozygous RhoB-deficient mice (RhoB+/−) and homozygous RhoB-deficient mice (RhoB−/−)." (PMID 36114582, 2022). "In our study, we showed that RhoB deficiency protected against colitis directly." (PMID 36114582, 2022). "As expected, RhoB+/− mice exhibited mild colitis in comparison with WT littermates, as reflected by body weight loss, disease activity index, colon length, histological score, and goblet cell numbers." (PMID 36114582, 2022). "WT mice cohoused with RhoB+/− or RhoB−/− mice developed mild colitis, the similar phenotype to that of RhoB+/− or RhoB−/− mice, indicating a transfer of RhoB+/− or RhoB−/− phenotype to WT mice after cohousing." (PMID 36114582, 2022). "Antibiotic treatment eliminated the difference in the severity of colitis including disease activity index, colon length, and histological score between WT and RhoB+/− mice." (PMID 36114582, 2022). "The immunohistochemical analysis revealed that RhoB was dramatically higher in colon tissues of severe colitis samples compared with that in healthy controls and mild colitis samples." (PMID 36114582, 2022). "Compared with wild type mice, RhoB+/− and RhoB−/− mice developed milder DSS-induced colitis and increased goblet cell numbers and IEC proliferation." (PMID 36114582, 2022). "We found that RhoB protein level was dramatically elevated in colonic epithelia of DSS-induced colitis mice." (PMID 36114582, 2022). "Considering that RhoB+/− mice had better effect on alleviating colitis symptoms than RhoB−/− mice, we investigated the role of RhoB in chronic colitis using RhoB+/− mice." (PMID 36114582, 2022). "As reflected by the disease activity index, colon length and histological score, RhoB+/−/RhoB−/− microbiota recipient mice exhibited increased resistance to colitis, suggesting gut microbiota contribute to the attenuated phenotype of RhoB+/− and RhoB−/− mice during colitis." (PMID 36114582, 2022). "Thus, the better effect of RhoB+/− than RhoB+/− in DSS-induced colitis is mainly a result from intestinal microbiome, indicating that RhoB-mediated intestinal microbiome alternation plays an important role in resistance to DSS-induced colitis." (PMID 36114582, 2022). "Our current findings showed that antibiotics treatment diminished RhoB expression during colitis." (PMID 36114582, 2022). "RhoB regulates multiple cell functions; however, its role in colitis is unexplored." (PMID 36114582, 2022). "Rapamycin treatment was found to aggravate the severity of colitis in both WT and RhoB−/− mice." (PMID 36114582, 2022). "Interestingly, we noted that RhoB+/− mice exhibited better effect on alleviating colitis symptoms than RhoB−/− mice." (PMID 36114582, 2022). "RhoB, a member of the small Rho GTPase family, exhibits rapid upregulation when the organism is induced by genotoxic stress, LPS, inflammatory cytokines, growth factors and toxins, and is involved in a variety of cellular processes; however, the role of RhoB in colitis remains unclear." (PMID 36590401, 2022). "Decreased weight loss, diarrhea, rectal bleeding, and disease activity index (DAI, a composite score used to evaluate the clinical manifestations of colitis) were observed in DSS-treated RhoB+/− and RhoB−/− mice compared with those in DSS-treated WT mice." (PMID 36114582, 2022). "To further define this relevance between RhoB and UC, we examined RhoB level in DSS-induced colitis in C57BL/6J mice." (PMID 36114582, 2022). "Here, we found RhoB was dramatically increased in colon tissues of ulcerative colitis (UC) patients and mice with DSS-induced colitis." (PMID 36114582, 2022).
colitis (continued). "Taken together, these results demonstrate that reduced level of RhoB increases intestinal SCFA-producing bacteria and SCFA concentrations, which are beneficial microbiome for protecting against DSS-colitis." (PMID 36114582, 2022). "We found that RhoB expression is increased in colons from patients with severe UC and mice with dextran sulfate sodium (DSS)-induced colitis." (PMID 36114582, 2022). "Collectively, these data indicate that decreased RhoB in epithelial cells enhances goblet cell numbers and promotes epithelial regeneration, which may lead to resistance to DSS-induced colitis and enhancing intestinal barrier integrity." (PMID 36114582, 2022). "We induced acute colitis using DSS in WT, RhoB+/−, and RhoB−/− mice." (PMID 36114582, 2022). "RhoB downregulation increases goblet cell numbers, promotes regeneration of the colonic epithelium, and changes intestinal microbiome (microbiota and metabolites), which consequently result in resistance to DSS-induced colitis." (PMID 36114582, 2022). "However, rapamycin treatment did not abolish the difference in the severity of colitis between WT and RhoB−/− mice, suggesting that the colitis phenotype in RhoB−/− mice is independent of autophagy." (PMID 36114582, 2022). "However, compared with WT mice, RhoB+/− or RhoB−/− mice after cohousing continued to show a persistent mild degree of colitis, although without significant difference." (PMID 36114582, 2022). "Therefore, some of the beneficial effects of P100K milk EVs on colitis might come from the reduction of the IL-9/miR-21/CLDN8 pathway, which would impact RhoB, reduce gut permeability and modulate the microbiota." (PMID 31601878, 2019).
liver cancer (5 papers, 2016 to 2024). An epithelial or non-epithelial malignant neoplasm that arises from the liver. "However, treated with MLN4924 blocked cullin neddylation, inactivated CRL and caused the accumulation of RhoB, which further induced apoptosis and suppressed proliferation of liver cancer cells." (PMID 37771770, 2023). "Cul2-RBX1 E3 ligase, as the main regulator, functioned for the ubiquitination and degradation of RhoB in liver cancer cells." (PMID 37771770, 2023). "The MLN4924-induced accumulation of RhoB seemed to contribute significantly to the anticancer activity of this drug in liver cancer." (PMID 27222660, 2016). "Furthermore, both CUL2 and RBX1 have been shown to contribute to the ubiquitination and degradation of the tumour suppressor RHOB in liver cancer." (PMID 35664333, 2022).
osteosarcoma (5 papers, 2017 to 2025). A usually aggressive malignant bone-forming mesenchymal neoplasm, predominantly affecting adolescents and young adults. "In osteosarcoma, miR-19 targets RhoB and down-regulates its expression, inhibiting the dephosphorylation of Akt1 protein and promoting tumor cell metastasis." (PMID 35538494, 2022). "Moreover, miR-21 influences the expression of Ras homolog family member B (RhoB), a protein involved in integrin signaling and cell survival in multiple myeloma, and modulates the anti-apoptotic protein Bcl-2 in osteosarcoma." (PMID 41463125, 2025). "ARHGEF3 downregulation may be associated with invasion, metastasis, and proliferation in osteosarcoma because this gene specifically activates RHOA and RHOB, which play a role in bone cell biology." (PMID 37315301, 2023). "In this present study, we found that dexamethasone (Dex) could induce the expression of the small G protein, RhoB, in mRNA and protein levels in the osteoblast-derived osteosarcoma cell lines MG-63." (PMID 28323887, 2017). "RNA sequencing identified RHOB as a top upregulated gene in both DDR- and Roc-treated osteosarcoma cells, but the Rho inhibitor Rhosin did not enhance the growth-inhibitory activity of (-)-DDR or (-)-Roc." (PMID 38947012, 2024).
rectal cancer (5 papers, 2017 to 2024). A primary or metastatic malignant neoplasm that affects the rectum. "Our earlier research in a clinical trial of preoperative RT in rectal cancer patients showed that RhoB overexpression was associated with later TNM stage, distant recurrence and worse survival in the RT patients but not in non-RT patients." (PMID 38355625, 2024). "Our previous study revealed an independent association between RhoB overexpression and poor survival in rectal cancer patients who underwent radiotherapy." (PMID 38355625, 2024). "Here the power of Ras homolog family member B (RhoB) protein as a biomarker in rectal cancer biopsy is examined from the standpoint of AI and machine learning." (PMID 36937315, 2023). "Ten‐fold cross‐validations of 5‐year survival prediction using RhoB expression in rectal cancer, using top three proposed models." (PMID 38014709, 2023). "Top three accuracies (%) obtained from 10‐fold cross‐validations of 5‐year survival prediction using RhoB and DNp73 expressions in rectal cancer." (PMID 38014709, 2023). "The use of AI for discovering RhoB as a potential biomarker captured on rectal-cancer biopsy illustrated in this study relieves the time-consuming, error-prone, and subjective task encountered by pathologists." (PMID 36937315, 2023). "In this study, we analyzed the expression levels of RhoB and DNp73 proteins in rectal cancer, as captured in immunohistochemical images, to predict the 5‐year survival time of two patient groups: one with preoperative radiotherapy and one without." (PMID 38014709, 2023). "Using IHC images of RhoB protein expression on rectal-cancer NATs, this study combines the methods of pre-trained convolutional neural networks (CNNs), nonlinear dynamics, and long short-term memory (LSTM) for classifying IHC images of the NATs." (PMID 36704244, 2022). "This study introduces the combination of pretrained CNNs and a support vector machine (SVM) algorithm for discovering the power of RhoB expression on IHC-stained biopsy samples obtained from two cohorts of rectal-cancer patients having less or more than 5 years of survival after surgery." (PMID 36937315, 2023). "This study introduces the integration of pretrained convolutional neural networks and support vector machines (SVMs) for classifying biopsy samples of immunohistochemical expression of protein RhoB in rectal-cancer patients to validate its biologic measure in biopsy." (PMID 36937315, 2023). "The results illustrate that the CNN-FRP-LSTM models are more favorable in terms of the combination of accuracy and computational complexity than other classification methods for predicting the 5-year survival of rectal-cancer patients using IHC images of RhoB expression on NATs." (PMID 36704244, 2022). "Furthermore, the main purpose of this study is to show that the predictive power of RhoB expression in rectal cancer biopsy can be discovered by the use of AI while our manual analysis could not reveal the prognostic capacity of the protein." (PMID 36937315, 2023). "The high statistical performance measures provided by the NASNet-Large & SVM strongly suggest the potential of RhoB expression captured on the IHC samples of the rectal-cancer biopsy as a protein biomarker for predicting the 5-year survival rate of rectal-cancer patients without undergoing pRT." (PMID 36937315, 2023).
diabetes (4 papers, 2020 to 2024). "Similar methods were used to induce diabetes in RhoB+/− and RhoB−/−, MMP9−/−, and leukotriene-deficient 5LO−/− mice to study the role of these proteins in T1DM." (PMID 38612647, 2024). "In urine exfoliated cells from patients with diabetes, we observed decreased expression of RHOB mRNA." (PMID 36127330, 2022).
pulmonary hypertension (4 papers, 2016 to 2020). Increased pressure within the pulmonary circulation due to lung or heart disorder. "RhoB plays a key role in the pathogenesis of hypoxia-induced pulmonary hypertension." (PMID 28395021, 2017). "Moreover, genetic deletion of RhoB attenuates development of chronic hypoxia-induced vascular remodeling and pulmonary hypertension in mice." (PMID 27121304, 2016). "Our study demonstrates that miR-223 regulation directly targets RhoB and MLC2 to affect vascular remodeling and hypoxia-induced pulmonary hypertension." (PMID 27121304, 2016).
skin cancer (4 papers, 2010 to 2018). "Further, human SCC tumor samples stained for phosphorylated histone H2AX, a marker for DNA double stranded breaks (DSBs), revealed the undifferentiated and RhoB-deficient human skin tumors had elevated levels of γH2AX expression." (PMID 29385717, 2018). "Indeed, RhoB-null mice have increased susceptibility to skin tumor carcinogenesis." (PMID 25548921, 2014). "Although RhoB was also shown to be dispensable for mouse development, rhoB nullizygous mice exhibited accelerated chemically induced skin tumors and increased efficacy of intraperitoneal tumor formation." (PMID 29385717, 2018). "RhoB knock-out mice develop normally but have enhanced carcinogen-induced skin tumor formation, in agreement with a role of RhoB as a tumor suppressor." (PMID 20822528, 2010).
anaplastic thyroid carcinoma (3 papers, 2014 to 2024). "The findings of their study revealed that RhoB played a significant role as a new mediator in crucial signaling pathways, indicating an additional potential target for therapeutic strategies in anaplastic thyroid cancer." (PMID 38420016, 2024). "This relationship is made further evident by another study demonstrating that the utilization of pan-HDAC inhibitor FK228 leads to upregulation of RHOB expression and promotes growth inhibition of anaplastic thyroid carcinoma cell lines." (PMID 31200451, 2019). "A recent study regarding anaplastic thyroid carcinoma was able to restore RHOB promoter activity after using shRNA constructs against HDAC6, effectively showing that HDAC6 does in fact repress the RHOB promoter." (PMID 31200451, 2019).
brain cancer (3 papers, 2013 to 2020). A primary or metastatic malignant neoplasm affecting the brain. "In patients with head and neck, lung, or brain cancers, RhoB protein levels are decreased as the tumors become more aggressive and invasive." (PMID 24223801, 2013). "Moreover, the expression of both RhoA and RhoB was tested in different types of brain cancer cells, and results showed that as the malignancy of the brain tumor increased, the levels of RhoA and RhoB expressions decreased." (PMID 32089990, 2020).
brain tumors (3 papers, 2018 to 2020). "Current histological diagnoses of brain tumors are complicated by similarities between the different grades, therefore, the idea of having a molecular confirmation with RhoA and RhoB could greatly improve the therapeutic approach." (PMID 29385717, 2018).
head and neck carcinoma (3 papers, 2007 to 2017). A carcinoma that arises from the head and neck region. "Loss of RhoB expression has been reported in other tumors such as Head and Neck carcinomas, brain tumors and lung tumors." (PMID 24223801, 2013). "Loss of expression of RhoB has been reported in other solid tumors such as Head and Neck carcinomas and brain tumors." (PMID 18047684, 2007). "It should be noticed that no deletion has been found in the RhoB gene in 12 head and neck carcinomas analyzed in another study." (PMID 18047684, 2007).
systemic sclerosis (3 papers, 2011 to 2026). A chronic disorder, possibly autoimmune, marked by excessive production of collagen which results in hardening and thickening of body tissues. "The aim of this study was to confirm the association of RHOB and FAM167A-BLK gene polymorphisms with susceptibility to systemic sclerosis (SSc) in a Chinese Han population." (PMID 25470816, 2014).
thyroid cancer (3 papers, 2014 to 2019). "Our results therefore identify RhoB upregulation as a key step for inhibition of thyroid cancer cell proliferation and therefore tumor progression via activation of p21." (PMID 25548921, 2014). "To explore TRβ function in thyroid cancer cell proliferation, we focused on analysis of RhoB, which is a target of TRβ and is expressed at very low levels in 130 human cancer cell lines." (PMID 25548921, 2014). "We next analyzed the effect of T3 treatment of AdTRβ- or AdLacZ-infected thyroid cancer cell lines on RhoB expression." (PMID 25548921, 2014). "Our findings therefore establish RhoB as a direct transcriptional target of liganded-TRβ in thyroid cancer cell." (PMID 25548921, 2014). "Our results identify RhoB upregulation as a key step for targeting thyroid cancer cell proliferation and tumor progression." (PMID 25548921, 2014). "Additionally, ligand-bound thyroid hormone receptor beta (TRβ) was found to activate the RhoB signaling pathway upstream of p21 in thyroid cancer cells resulting in an inhibition of proliferation both in vitro and in vivo that required upregulation of RhoB." (PMID 29385717, 2018). "Thus, induction of RhoB mRNA and protein expression are T3/AdTRβ-dependent in thyroid cancer cell lines." (PMID 25548921, 2014). "To understand the functional consequences of ligand-bound TRβ effects on downstream signaling pathways in thyroid cancer cells, we focused on RhoB that is a member of the Ras superfamily of isoprenylated small GTPases, which regulate actin stress fibers and vesicle transport." (PMID 25548921, 2014). "The combined results indicated that ligand-bound TRβ induced the expression of RhoB which acts as a critical mediator of the cellular response to FTI and inhibits thyroid cancer cell proliferation and migration." (PMID 25548921, 2014).
astrocytic tumor (2 papers, 2020). A glial tumor of the brain or spinal cord showing astrocytic differentiation. "Concordant with the results for RhoB, Khalil and El-Sibai observed low expression of RhoA and RhoB in astrocytic tumors." (PMID 33162807, 2020). "RhoA and RhoB expression was significantly reduced in astrocytic tumors and their levels were inversely proportional to tumor grade, ie, lower expression was associated with a higher grade and therefore a more aggressive neoplasm." (PMID 33327966, 2020).
Breast Invasive Carcinoma (2 papers, 2020 to 2021). "On the other hand, TCGA data supports RHOB as a proto-oncogene amplified in the majority of all major tumors, including GBM and invasive breast cancers." (PMID 34680293, 2021).
endothelial dysfunction (2 papers, 2023 to 2024). In vascular diseases, endothelial dysfunction is a systemic pathological state of the endothelium (the inner lining of blood vessels) and can be broadly defined as an imbalance between vasodilating and vasoconstricting substances produced by (or acting on) the endothelium. "RhoB is targeted directly by miR-21, and this leads to suppression of its expression and activation of kinase which leads to endothelial dysfunction, inflammation and development of PH." (PMID 37646902, 2023). "Furthermore, it is known that miR-21 represses RhoB expression in endothelial cells, leading to angiogenesis inhibition, and regulates superoxide dismutase 2 (SOD2), as well as Sprouty 2, resulting in NO (nitric oxide) reduction and endothelial dysfunction." (PMID 38921830, 2024).